BRCA1 (BRCA1 DNA repair associated)
Diseases named in the same sentence as BRCA1 in open-access papers (continued):
Sharing a sentence is not in itself a finding about the gene and the disease.
cancer (continued). "We detected the BRCA1 promoter methylation in 25 of 268 (9.3%) cancer-free women and in 20 of 295 (6.8%) delivering women." (PMID 30049288, 2018). "This is well exemplified by the molecular epidemiology of BRCA1 and BRCA2 mutations, which show significant global variations with regard to contribution in regional cancer incidence as well as to mutation spectrum." (PMID 30211169, 2018). "We have previously shown that the MGMT gene is methylated in WBC of cancer-free BRCA1 methylation carriers." (PMID 30049288, 2018). "Recently, the cluster regions within BRCA1 and BRCA2 associated with specific cancers have been well established." (PMID 30089478, 2018). "The pathogenesis of BRCA1/2-driven cancers usually involves somatic inactivation of the wild-type copy of the involved gene; therefore, malignant cells are characterized by tumor-selective deficiency of DNA repair." (PMID 30211169, 2018). "The popular actress and human rights advocate, Angelina Jolie, was one such woman diagnosed with a breast cancer-causing BRCA1/2 genetic mutation, who opted to undergo PSO to reduce her risk of developing cancer." (PMID 30766717, 2018). "Therefore, we used yeast as genetic model to investigate the functional interaction between BRCA1 missense variants and DNA repair and to address whether this model system could be useful to evaluate the cancer risk in patients carrying mutations in distinct DNA repair genes." (PMID 30283497, 2018). "For the 176 respondents, the mean age was 49.1 ± 13.68 years (range: 22–85);; 101/175 (57.7%) had a personal history of cancer related to BRCA1/2." (PMID 30308700, 2018). "The FANCC knockout rearrangement pattern comprised mainly short tandem duplications and short deletions (<10 Kb) and also had other rearrangement classes but essentially echoed those of BRCA1-null cancers." (PMID 29717121, 2018). "To date, the scope of BRCA1 and BRCA2 testing has been substantially larger than any other cancer predisposition gene, yet the ability to look across the spectrum of publicly available data has not been coordinated." (PMID 30586411, 2018). "Although PARP inhibitors are now exploited clinically to treat BRCA1- and BRCA2-mutated cancers, the nature of the DNA structures on which PARP enzymes are “trapped” by these inhibitors is unclear." (PMID 29983321, 2018). "BRCA1 (originally breast cancer 1; currently BRCA1) critically contributes to DSB repair in central neurons and neuronal reductions." (PMID 30181485, 2018). "Second, tandem duplications were larger in CCNE1-activated HCC (median = 39 kb) than in CCNA2-activated HCC (22 kb), and smaller in BRCA1-altered breast (9 kb) and ovarian (10 kb) cancers." (PMID 30531861, 2018). "The identification of BRCA1 and BRCA2 germline mutations as predictors of cancer susceptibility significantly improved the diagnosis and prevention of hereditary breast and ovarian cancers (HBOC)." (PMID 29338689, 2018). "Several genes account for a large proportion of variant/drug interactions (e.g., EGFR, KIT, ERBB2, BRCA1, PDGFRA), reflecting interest in therapeutically exploiting a relatively limited number of cancer driver genes." (PMID 30053901, 2018). "For the subset of 23 deceased BRCA1/2 carriers, only 4 had prior clinical testing and the percentage with syndromic cancer diagnoses was 47.8%, which is similar to published observations of clinically ascertained cases." (PMID 30646163, 2018). "Syndromic cancer diagnoses were present in 11 (47.8%) of the 23 deceased BRCA1/2 carriers and in 56 (20.9%) of all 267 BRCA1/2 carriers." (PMID 30646163, 2018).
cancer (continued). "Although the BRCA1 function is important and complete loss of function can be detrimental, downregulation of the wild-type BRCA1 in cancer cell populations can provide benefits in the therapeutic utility of PARP-inhibitor monotherapy." (PMID 30002440, 2018). "Three of the pan-cancer PTV-ALFRED genes (BRCA1, BRCA2, and ATM) and all four individual cancer type PTV-ALFRED genes were individually significantly enriched for rare PTVs in cases versus controls (nominal P < 0.05)." (PMID 29973584, 2018). "Secondly, FOXP3 represses several key target genes in cancer development, such as BRCA1, CD44, HER2/ERBB2, and SKP2, providing a strong link between FOXP3 and DNA repair system, as well as FOXP3 and cell cycle regulation." (PMID 30011797, 2018). "The object of our study was to shed light on potential contribution of BRCA1 to the metabolic features of cancer cells, including the so-called ‘‘Warburg effect’’." (PMID 29584711, 2018). "However, women carrying BRCA2 mutations show clinical courses with better prognoses than those carrying BRCA1 mutations, in terms of a longer time to first relapse as well as fewer relapses, but both carriers showed higher survival rates than expected for the stage and grade of their cancers." (PMID 30119676, 2018). "Global protocols and standards differ widely when it comes to analyzing variants in the BRCA1 and BRCA2 cancer susceptibility genes." (PMID 29479477, 2018). "Pathway analysis revealed that SPP1 overexpression affected the expression levels of BRCA1 and CDC20, which have been reported to be associated with several cancers types." (PMID 30517191, 2018). "Aside from cancer therapy using BRCA1 tBRCT inhibitors, however, the potential utility of selective tBRCT inhibitors in the treatment of other diseases remains relatively under-explored." (PMID 29606576, 2018). "Though there was reduction of mutant BRCA1 mRNA, its protein was expressed in cancer cells when HCC1937 were co-cultured with cmCAFs probably due to increased stability of mutant BRCA137." (PMID 30224826, 2018). "Based on the results, we found that STAT6, a cancer-related TF, regulated FOS and FOSB, while FOS and EGR1 were coregulated by 2 cancer-related TFs, including BRCA1 and SP1, respectively." (PMID 30228980, 2018). "In the last years, many groups have deep investigated the role of defective HR mechanisms in cancer: the so-called “BRCAness” status is defined as the presence in tumor cells of alternative mechanisms impairing BRCA1/2 functions, or the alteration in HR genes." (PMID 30234015, 2018). "Due to their synthetic lethal relationship, in HR-defective BRCA1/2-mutant cells, that is, cancer cells, chemical inhibition of PARP-1 is selectively toxic in combination with conventional chemotherapy." (PMID 30200453, 2018). "Recent epidemiologic studies have reported an increased risk of cancer among individuals with higher levels of APC, BRCA1, and RASSF1 promoter methylation in tissue or in blood." (PMID 29953441, 2018). "Hypermethylation of the CpG islands was one of the major factors underlying the inactivation of tumor suppressor genes such as Rb, VHL, hMLH1, and BRCA1 in cancer." (PMID 29462183, 2018). "Historically, three founder mutations in the BRCA1/2 (OMIM 113705; OMIM 600185) genes have been the focus of cancer risks within the Ashkenazi Jewish (AJ) population." (PMID 30152102, 2018). "Increased surveillance of healthy BRCA1/2 male carriers is still controversial, even if higher cancer risks are recognised." (PMID 29456621, 2018). "The GEMO resource is available to internal and external researchers who can apply for blood DNA and data for use in ethically approved, peer reviewed collaborative and interdisciplinary projects on the genetic epidemiology of cancer in BRCA1/2 families." (PMID 30430080, 2018).
cancer (continued). "Mutations in genes of the breast cancer susceptibility gene (BRCA) pathway, namely, BRCA1, BRCA2, and PALB2, can provide useful information for the efficacy of platinum-based or poly ADP-ribose polymerase inhibitors chemotherapeutic regimens." (PMID 29802286, 2018). "The Genetic Modifiers of BRCA1 and BRCA2 (GEMO) Group is the French multidisciplinary, collaborative framework for the investigation of genetic factors modifying cancer risk in Hereditary Breast and Ovarian cancer (HBOC) families segregating BRCA1/2 PVs." (PMID 30430080, 2018). "BRCA1 promoter methylation was also examined in PDX samples upon cancer recurrence following in vivo treatment with either cisplatin or rucaparib." (PMID 30266954, 2018). "Germline mutations in either BRCA1 or BRCA2 are associated with increased predisposition to breast, ovarian and other cancers." (PMID 29545922, 2018). "First, the number of RS1 rearrangements was higher in CCNA2-activated HCC (median = 269) than in CCNE1-activated HCC and BRCA1-altered breast and ovarian cancers." (PMID 30531861, 2018). "Variation in cancer risks within or between BRCA1/2 families, with respect to age at diagnosis or type of cancer, can be explained by other genetic factors and/or lifestyle and reproductive factors." (PMID 30430080, 2018). "Although millions of women, and more recently men, at risk for cancer have been tested for germline genetic variants in BRCA1 and BRCA2, diagnostic sequencing has continued to identify variants with uncertain relevance to cancer risk." (PMID 30586411, 2018). "Both BRCA1 and BRCA2 are oncosuppressor genes involved in DNA repair and are commonly mutated in a number of cancers." (PMID 29346284, 2018). "Notable exceptions are the BRCA1 and the BRCA2 genes, whose mutations have high penetrance and are found in nearly 40% of cancer patients." (PMID 30263092, 2018). "Families and individuals who previously have tested negative for founder mutations should systematically be offered retesting with sequencing and MLPA in order to identify healthy BRCA1/2 carriers and enable them to prevent cancer." (PMID 29339979, 2018). "This shows that cancer-free women and newborns have similar frequencies of BRCA1 promoter methylation in their WBC." (PMID 30049288, 2018). "Pathogenic variants in the highly penetrant susceptibility genes BRCA1 and BRCA2 confer an increased lifetime risk of breast, ovarian and other cancers." (PMID 30400234, 2018). "In this study, we have attempted to compile pathogenic and likely pathogenic BRCA1 and BRCA2 variants identified in the main Genetic Cancer Risk Assessment centers in Brazil." (PMID 29907814, 2018). "53BP1 controls a specialized non-homologous end joining (NHEJ) pathway that is essential for adaptive immunity, yet oncogenic in BRCA1 mutant cancers." (PMID 30559443, 2018). "For example, our BRCA1-positive patient has been advised to undergo the relevant cancer screening for males, but the more significant risks with this variant are for his close female relatives." (PMID 30487145, 2018). "We performed targeted sequencing analyses of all coding exons of BRCA1, BRCA2, and PALB2, as well as sequencing mutational hotspots of 50 cancer-associated genes in the 42 PDAC tumors with paired normal tissues using a next-generation sequencing platform." (PMID 29802286, 2018). "Fullyplatinum-sensitivity was characterized by lower BRCA1/2 mRNA-expression in BRCA1-wildtype cancers in comparison to platinum-refractory OC." (PMID 30111871, 2018). "This study is the first to clarify the critical role of BRCA1 methylation zygosity in the response of carcinomas to PARPi and has potentially important clinical implications." (PMID 30266954, 2018).
cancer (continued). "Germ line mutations in BRCA1 and BRCA2 genes generally account for hereditary breast/ovarian cancer and, when found, permit to predict the life-time risk for these cancers." (PMID 28559958, 2017). "The identification of a carrier of a pathogenic variant in BRCA1 or BRCA2 can significantly impact their medical management, as well as that of at-risk family members, since several cancer risk-reducing strategies are available." (PMID 29161300, 2017). "Defective homologous recombination (HR)-mediated DNA repair as a result of mutations in BRCA1/BRCA2 genes is related to genomic instability and generates a unique sensitivity in cancer cells to DNA-targeting agents, which induce irreversible DNA damages." (PMID 29156578, 2017). "Knock out mouse model studies of CHK1, MCM4, and RAD1 all show embryonic lethality in homozygous null mice and increased cancer incidence in heterozygotes, similarly to BRCA1/2, which makes them compelling and worthy of following up with functional studies." (PMID 28591191, 2017). "Rad51 nucleofilament assembly requires the help of mediator proteins, such as breast cancer 1 and 2 (BRCA1 and BRCA2) and several Rad51 paralogues, but the exact mechanisms that underlie this process are only partially understood." (PMID 28471392, 2017). "It was statistically significant that 34 tumors with low expression of BRCA1 were sensitive to platinum, as well as 43 cancers with high expression of miRNA-9." (PMID 29021870, 2017). "When classifying BRCA1 or BRCA2 mutant samples from sporadic cancers we achieved an AUC = 0.660; however, classification of only germline BRCA2 mutant tumors was inaccurate (AUC = 0.528)." (PMID 29146938, 2017). "Despite these therapeutic advances in patients with germline BRCA1/2 mutant cancers, PARP inhibitor therapy still results in variable responses between patients, and secondary resistance to therapy is inevitable." (PMID 29262651, 2017). "We report a high metastatic potential of β-hCG in BRCA1 defective cancers as inhibition of β-hCG can result in 15% and 55% more reduction in migration and invasion respectively in BRCA1 mutant than in wild-type cancer cells." (PMID 28869585, 2017). "An unexpected finding was that, in addition to inducing EZH2 expression in cancer cells, MUC1-C was detectable in complexes with EZH2 on the CDH1 and BRCA1 promoters, invoking the notion that MUC1-C associates with EZH2." (PMID 28785086, 2017). "The dependence of BRCA1/2 cancers on FANCD2 in promoting Alt-EJ makes exploitation of the FA pathway an attractive option for targeted therapies." (PMID 28239445, 2017). "When a cancer arises from defects in one DNA repair pathway, such as HR in the BRCA1/2-mutant malignancies, they become addicted to other DNA repair pathways for survival during replication." (PMID 28756516, 2017). "The various related and distinct functions of BRCA1 and BRCA2 have made it difficult to pinpoint the function of these gene products responsible for the closely related cancer phenotypes caused by their gene defects." (PMID 27452521, 2017). "Our results also indicate that intracellular HA produced by HAS1 is associated with the BRCA1-RHAMM-microtubule complex, which implies a possible mechanistic role in cancer initiation and progression." (PMID 29137675, 2017). "In HBOC, all studies consistently indicated that genes besides BRCA1 and BRCA2 are mutated and confer a moderate- to high-cancer-risk." (PMID 28146134, 2017). "BRCA1/2 cancers have been shown to rely on Alt-EJ for stabilization of replication forks and DSB repair in the absence of functional HR." (PMID 28239445, 2017). "This is precisely what happened in cancer cells defective for HRR pathways, as a result of BRCA1/2 mutations." (PMID 28055979, 2017). "Since β-hCG is upregulated in BRCA1 defective but not in wild-type condition, β-hCG would have a major role in tumorigenesis in BRCA1 defective cancers." (PMID 28869585, 2017).
cancer (continued). "Homologous recombination is defective in cancer cells with mutant BRCA1 or BRCA2 genes, leading to more genetic abnormalities." (PMID 28591715, 2017). "Several reports show that BARD1 has an additional BRCA1-independent tumor suppressor function in cancer that is antagonized by the expression of BARD1 isoforms." (PMID 29292755, 2017). "This study indicates that the mechanism of synthetic lethality in RAD52-depleted BRCA1 mutant cancer cells depends on the endonuclease EEPD1." (PMID 29145865, 2017). "We also examined survival of MDA-MB-436 BRCA1-/- cancer cells after 18 h treatment with 10 mM HU, which causes replication fork stalling and collapse." (PMID 29145865, 2017). "Our results on pitaya extract can be reconciled with more general findings in cancer biology that tumors activate DNA damage response pathways such as BRCA1/2 upon exposure to DNA-damaging agents." (PMID 28761624, 2017). "In a separate line of investigation, RAD52 was identified as essential for viability of cancer cells with defects in various HR proteins including BRCA1, BRCA2, and partner and localizer of BRCA2 (PALB2)." (PMID 29145865, 2017). "In an experimental model system, cancer stem cells in BRCA1 mutant TNBC which were resistant to PARP inhibition showed higher RAD51 expression." (PMID 29287594, 2017). "Taken together, these data show that dysplastic lesions, which are premalignant lesions, also shed transforming factors that turn BRCA1-KO cells into cancer." (PMID 28854931, 2017). "Genome-wide studies of patients carrying pathogenic variants (mutations) in BRCA1 or BRCA2 have reported strong associations between single-nucleotide polymorphisms (SNPs) and cancer risk." (PMID 28145423, 2017). "The most popular example exploits the dependency of BRCA1 and BRCA2 deficient cancers on the base excision repair protein PARP1, leading to the development of PARP inhibitors (PARPi)." (PMID 28239445, 2017). "There was also a significantly reduced OS for patients with germline BRCA1 mutant cancers versus those harboring BRCA2 mutant cancers (515 vs 937 days; HR: 0.49, 95% CI 0.29-0.83; p=0.007)." (PMID 29262651, 2017). "In other cancers, response to PARP inhibitors has been associated with defects in DNA damage response (DDR) (e.g., mutations in BRCA1/2, ATM)." (PMID 28212573, 2017). "Five of 114 (4.4%) of ER+ HER2+ cancers had mutations (4 BRCA2) and 4/45 (9%) of ER− HER2+ (3 BRCA1)." (PMID 27796713, 2017). "Germline mutations in the BRCA genes (BRCA1, BRCA2) predispose individuals to develop several kinds of cancer, including that of the breast." (PMID 29138528, 2017). "BRCA1/2-defective cancer cells exhibit enhanced sensitivity to PARP inhibitors, as they are unable to efficiently repair the resultant DNA double-strand breaks, which leads to cell death." (PMID 29104272, 2017). "In summary, our data demonstrate that RDR is a relatively frequent phenomenon among patients treated with PARP inhibitors, especially those with germline BRCA1/2 mutant cancers." (PMID 29262651, 2017). "The mean age at cancer diagnosis in the BRCA1-pathogenic group was 41.6 years, in the VUS-BRCA1 group this value decreased to 37.2 years, and for the WT-BRCA1 group the mean age was 36.5 years." (PMID 27926510, 2017).